ABCC1 (ATP binding cassette subfamily C member 1 (ABCC1 blood group))
Diseases named in the same sentence as ABCC1 in open-access papers (continued):
Sharing a sentence is not in itself a finding about the gene and the disease.
cancer (300 papers, 1999 to 2026). A tumor composed of atypical neoplastic, often pleomorphic cells that invade other tissues. "In a cohort-based association study involving 111 cancer patients, genotyping of ABCC1/MRP1, ABCC2/MRP2, and ABCC4/MRP4 was conducted using real-time PCR with TaqMan probes." (PMID 41751467, 2026). "Given the pump‐like function of ABC transporters, the impact of KSQ‐4279 on ABCB1‐, ABCG2‐, and ABCC1‐caused doxorubicin efflux was further evaluated by quantifying the change of doxorubicin inside cancer cells over time." (PMID 41328326, 2025). "ABC transporters, particularly ABCB1 and ABCC1, are widely expressed in multiple cancer types and are strongly implicated in multidrug resistance, which severely limits the effectiveness of chemotherapy." (PMID 39679367, 2024). "Our results confirmed that age at diagnosis and the G allele of the ABCC1 rs246240 SNP are significantly associated with VIPN in pediatric cancer patients." (PMID 39201483, 2024). "Our findings suggest that both age at diagnosis and the SNP ABCC1 rs246240 are associated with an increased risk of VIPN in pediatric cancer patients (p = 0.016 and p = 0.006, respectively)." (PMID 39201483, 2024). "ABCC1 has been implicated in human pathologies aside from cancer, including age-related macular degeneration, cardiovascular disease, some neurologic disorders, and regulation of oxidative stress." (PMID 37438132, 2023). "The multidrug resistance protein 1 (MRP1) encoded by ABCC1 was initially identified as a factor of cancer multidrug resistance." (PMID 38102848, 2023). "The well-known multidrug resistance-associated protein 1 (ABCC1) is a major player in cancer related multidrug resistance and has been well investigated in the management of drug-resistant tumors." (PMID 36118882, 2022). "Elevated ABCC1 levels have been found in many cancers and were associated with unfavorable outcomes." (PMID 35760832, 2022). "Previous studies in other cancers have associated ABCC1 (rs3743527, rs246221, rs4148350) with higher cardiotoxicity." (PMID 35456712, 2022). "Among 49 identified members, P-glycoprotein (ABCB1), breast cancer resistance protein (ABCG2) and MDR-associated protein 1 (ABCC1) have been well-clarified to play critical roles in the promoting MDR phenomenon in cancer." (PMID 36559089, 2022). "Although overexpression of other ABC transporters, including MRP1/ABCC1, has also been implicated in cancer MDR, this review focuses on P-gp and ABCG2." (PMID 34993424, 2021). "Cancer cells are able to produce multidrug resistance proteins, such as multidrug resistance protein 1, and multidrug resistance-associated protein 1 (ABCC1), which causes drug resistance." (PMID 31866857, 2019). "Overexpression of ABCC1 has been shown to be associated with resistance in many cancer types including lung, breast and prostate cancers." (PMID 34322663, 2019). "We determined that our established PTX-resistant cancer cells display ABCB1/ABCC1-associated cross-resistance to chemically different drugs such as 5-fluorouracil, docetaxel, and cisplatin." (PMID 27284014, 2016). "Although the drug transporters ABCG2, ABCB1 and ABCC1 have been majorly implicated in cancer drug resistance, recent studies have associated ABCC3 with multi drug resistance and poor clinical response." (PMID 27171227, 2016). "Of particular interest, the levels of the multidrug resistance-associated protein-1 (MRP1) encoded by the ABCC1 gene were significantly higher in the MUC1-high cancer cells." (PMID 27029067, 2016). "Non‐toxic concentrations Saq‐nitric oxide caused sensitization of ABCB1‐, ABCC1‐ or ABCG2‐overexpressing cancer cells to chemotherapy." (PMID 26864945, 2016). "The ATP-dependent transmembrane proteins, P-glycoprotein (P-gp, ABCB1) and multidrug resistance-associated protein 1 (MRP1, ABCC1) are primary contributors to MDR in cancer." (PMID 26082317, 2013).
cancer (continued). "This superfamily is composed of numerous pumps, including P-glycoprotein (also called ABCB1; its expression is detected in many cancers), multidrug resistance proteins (including ABCC1, or multidrug resistance-associated protein 1), and breast cancer resistance protein (BCRP/ABCG2)." (PMID 40869256, 2025). "Multivariate analysis confirmed that the independent variables associated with VIPN to any degree in pediatric cancer patients were age at diagnosis (OR = 1.33; 95% CI = 1.07–1.75; p = 0.016) and the ABCC1 rs246240—G allele (OR = 12.45; 95% CI = 2.26–100.42; p = 0.006; G vs. AA)." (PMID 39201483, 2024). "Likewise, a bispecific aptamer (MRP1-CD28) was used to guide CD28 agonistic aptamers to cancer stem cells expressing multidrug resistance-associated protein 1 (MRP1, also called ABCC1), which is ubiquitously expressed in aggressive tumors." (PMID 35189921, 2022). "Additionally, data from the UCSC Cancer Genomics Browser8 showed that high ABCC1, CHAC1, and GSS expression was associated with decreased disease-specific survival (DSS) and progression-free interval (PFI) (p < 0.001)." (PMID 34386492, 2021). "Therefore, blocking or inactivating transmembrane proteins, such as multidrug resistance protein 1 (MDR1, also known as P-gp and ABCB1) and MDR-associated protein 1 (MRP1/ABCC1), provides potential cancer therapies targeting MDR." (PMID 33669877, 2021). "Two of the most widely studied efflux pumps, MDR-1 P-gp/P-170, the gene product of MDR-1 (ABCB1) and MRP-1 (ABCC1) which encodes a 190 kDa membrane protein have both been demonstrated to pump a wide variety of the most commonly used cancer drugs out of tumour cells." (PMID 19552816, 2009). "Our results align with studies indicating that ABCC1 mislocalization increases chemotherapy sensitivity in cisplatin‐ and venetoclax‐resistant cancers." (PMID 39844613, 2025). "The multidrug resistance-associated protein-1 (MRP1 or ABCC1), and breast cancer resistance proteins (BRCP or ABCG2) are crucial MDR-associated ABC transporters." (PMID 40260304, 2025). "In conclusion, this study highlights the critical role of C1GALT1‐mediated O‐glycosylation in regulating the surface localization and stability of ABCC1, suggesting potential implications for cancer drug resistance." (PMID 39844613, 2025). "ABCB1, ABCC1, and ABCG2 transporter overexpression and COX-2 overexpression are typically linked in cancer." (PMID 40253988, 2025). "Mir-1207-5p normally targets ATP-binding cassette subfamily C member 1 (ABCC1), a well-established mediator of multidrug resistance by introducing efflux pumps to cancer cells, to reduce its effect in chemoresistance development." (PMID 40781643, 2025). "KSQ‐4279, an USP1 inhibitor in clinical trial, widely reversed multidrug resistance in refractory cancers by competing for the drug‐binding pockets of ABCB1/ABCG2/ABCC1 and blocking chemotherapeutic drugs’ efflux." (PMID 41328326, 2025). "KSQ‐4279 was shown to significantly elevate the antitumor function of multiple conventional chemotherapeutic drugs in MDR cancer cell lines driven by ABCB1/ABCG2/ABCC1 overexpression in vitro independently on its own cytotoxicity." (PMID 41328326, 2025). "ATP binding cassette subfamily C member 1 (ABCC1), known for contributing to chemotherapy resistance by transporting chemotherapeutics out of cancer cells, also has been shown to export cGAMP." (PMID 38659582, 2024). "The antioxidant reduced glutathione (GSH) is the prime substrate of ABCC1, which is often overexpressed in cancers due to the phenomenon of multidrug resistance." (PMID 39313842, 2024). "ABCC1 (MRP1) is a substrate for doxorubicin, and previous reports have demonstrated that ABCC1 is linked to doxorubicin resistance in multidrug-resistant cancer cells." (PMID 38413011, 2024). "Therapeutically, ABCC1 activators would be ideal lead molecules in both cancer and Alzheimer’s disease research." (PMID 39313842, 2024).
cancer (continued). "ABCC1 extrudes many important cancer chemotherapeutics, including doxorubicin, vincristine, methotrexate, etoposide, and irinotecan." (PMID 39337925, 2024). "This short review mainly focuses on those three ABC transporter members (ABCB1, ABCC1 and ABCG2), which are predominantly linked to the phenomenon of MDR in cancer therapy." (PMID 36677553, 2023). "We also identified MRP1 (ABCC1), a protein responsible for chemoresistance and typically upregulated in cancer cells, and ITGB4, which has a key role in tumorigenesis." (PMID 37295717, 2023). "The MDR to chemotherapeutic drugs in cancer cells is mediated through a mechanism involving P-glycoprotein (P-gp, or MDR1), multidrug resistance-associated protein 1 (MRP1 or ABCC1), or breast cancer resistance protein (BCRP or ABCG2)." (PMID 37990267, 2023). "The overexpression of P-gp, ABCG2, and ABCC1 is one of the major impediments to successful chemotherapy for cancer patients." (PMID 37444569, 2023). "There are only 13 different types of ABC transporters that have been found to play a part in drug resistance in cancer (ABCC1/2/3/4/5/6/10, ABCB1/2/5, ABCA2/3 and ABCG2)." (PMID 37569598, 2023). "ABCC1 is frequently overexpressed in drug-selected, multidrug-resistant cancer cell lines, and Abcc1−/− cells show tissue-specific hypersensitivity to cytotoxic xenobiotics like etoposide, vincristine, or methoxychlor." (PMID 37438132, 2023). "Silencing TM expression enhanced the anti-cancer effect of curcumin, and in addition to that, TM expression levels influenced the modulation of ABCC1, LRP1, and MDR1 drug-resistant-related genes." (PMID 37239055, 2023). "ABCC1 transports drugs to the extracellular substances, thereby reducing the drug concentration and generating drug resistance in cancer." (PMID 35342392, 2022). "There were no significant changes in gene expression levels for the seven other cancer genes (ABCC1, ALK1, BRCA1, DHRS2/HEP27, EGFR, ERBB2, and ERCC1)." (PMID 35743133, 2022). "ABCC1 is also known as multidrug resistance-associated protein 1 (MRP1) and causes chemotherapy resistance in various cancers." (PMID 36672755, 2022). "In ATC, high expression levels of ABCB1, ABCC1 and ABCG2 observed in several cell lines and tissues, were associated with cancer drug resistance." (PMID 35837087, 2022). "ABCB1 and ABCC1 promote the MDR phenotype on a variety of cancer models, including the FEPS cell line." (PMID 35719932, 2022). "Many drugs have already been developed to block ABCC1 transport to prevent chemoresistance in cancer." (PMID 32878879, 2021). "Considering the similar cancer spectrum between ABCC1 and betulin as described in the introduction section, we herein focused on the effectiveness of betulin influenced by ABCC1 overexpression." (PMID 33718236, 2021). "The results indicated that ABCC1 overexpression can confer resistance to betulin in cancer cells expressing ABCC1." (PMID 33718236, 2021). "It should be noted that other MDR-related ABC transporters such as ABCB1 and ABCC1 also actively mediate the drug resistance in cancer treatment." (PMID 34336849, 2021). "ABCC1 can thus mediate these features of cancers by exporting intracellularly generated S1P out of cancer cells and contribute to this “inside-out” signalling." (PMID 33801148, 2021). "Overexpression of ABCC1 is considered as one of the mechanisms that elicits MDR development in cancer cells due to its capacity to expel the chemotherapeutic drugs from the cells." (PMID 31991926, 2020). "Conversely, the exposure of cancer cells to the ODEP electrical conditions of 7–10 Vpp and 3–5 MHz did not significantly alter the cell viability, cell metabolic activity, and the EpCAM, VIM, and ABCC1 gene expression of cancer cells." (PMID 32560153, 2020).
cancer (continued). "The most studied members of the ABC-family of drug efflux pumps in cancer are ABCB1/MDR1/P-gp (P-glycoprotein), ABCC1 and ABCC2 (multi-drug resistance associated proteins 1 and 2; MRP1 and MRP2 respectively), and ABCG2 (breast cancer resistance protein; BCRP)." (PMID 32382711, 2019). "ABCC1 functions as a transporter, mediates export of drugs from the cytoplasm, and also confers resistance to anti-cancer drugs." (PMID 31380278, 2019). "For example, Slc2a1 (Glut1) was clustered together with Cldn5 (claudin 5) and Abcg2 (the breast cancer protein) in both cerebral structures, but it was clustered closely only with Abcc1 (multidrug resistance protein 1) in the hippocampus." (PMID 30298005, 2018). "The most recurrent alteration observed was elevation of ABCC1 expression in 48 patients receiving doxorubicin and/or paclitaxel from across six cancer types." (PMID 29783934, 2018). "The overexpression of MRP1/ABCC1 has also been shown to allow multidrug resistance to cancer chemotherapy." (PMID 30018187, 2018). "The cytotoxicity assay indicated that the IC50 values of olmutinib for ABCB1-, ABCG2-, and ABCC1-overexpressing cancer cells (KB-C2, NCI-H460/MX20 and KB-CV60) were 11.42, 12.19, and 17.14 μM." (PMID 30356705, 2018). "The most known ABC transporters are ABCB1 and ABCC1, involved in the multidrug resistance phenotype in cancer, given their participation in cellular detoxification." (PMID 29491856, 2018). "Of these, ABCB1/P-gp, ABCC1/MRP1, and ABCG2/breast cancer resistance protein are primarily associated with MDR." (PMID 29670920, 2018). "Previous research in cancer cells has shown that the ABCC1 promoter is hypomethylated but that the methylation status is not correlated with ABCC1 gene expression." (PMID 28800122, 2017). "Further, since many drugs are good substrates for ABCC1, its overexpression results in multidrug resistance, especially in cancer." (PMID 28800122, 2017). "The second MDR assay with specific MDR inhibitors showed that verapamil and MK-571 increased intracellular dye concentrations, confirming the involvement of the ABCB1 and ABCC1 in the eATP-induced efflux activity in two cancer cell lines." (PMID 29152126, 2017). "ABCC1 also leads to resistance to a wide range of anticancer drugs, and extensive evidence indicates that resistance of cancer cells to mitoxantrone, saquinavir, epipodophyllotoxins, and anthracyclines is mediated by ABCC1." (PMID 28646911, 2017). "ABC proteins responsible for multidrug resistance in human cancers include the multidrug resistance protein 1 (MRP1/ABCC1), P-glycoprotein (P-gp/ABCB1), and the breast cancer resistance protein (BCRP/ABCG2)." (PMID 28409029, 2017). "It is unclear the reason(s) for this disparity in the cancer cells, but in KCM, BxPC3 and Capan-1 cells, the cytoplasmic tail motif of MUC1 associated directly with the promoter region of the Abcc1/ABCC1 gene." (PMID 27029067, 2016). "Other important ABC transporters implicated in MDR of cancers include MRP1 and MRP2 (MDR1-related protein 1 and MDR-related protein 2) encoded by ABCC1 and ABCC2 genes, respectively." (PMID 27756418, 2016). "ABCB1, ABCC1 and ABCG2 are the ABC transporters most frequently been associated with MDR in cancers." (PMID 27689338, 2016). "Elevated expression of membrane drug efflux pumps such as P-glycoprotein (P-gp, ABCB1), multidrug resistance protein 1 (MRP-1, ABCC1) and ABCG2 is a frequent cause of MDR in human cancers." (PMID 25635866, 2015). "Apparently, the role of ABCC1 as predictive biomarker and potential drug target in human cancers raises further interest." (PMID 25078270, 2014). "Despite already accumulated knowledge on ABCC1 there are significant gaps in understanding its role in cancer therapy and prognosis which preclude clinical applications." (PMID 25078270, 2014). "The rs35605 SNP in ABCC1 have a significant impact on the pharmacokinetics and pharmacodynamics of irinotecan in advanced cancer patients." (PMID 25268163, 2014).
cancer (continued). "The clinical relevance of ABCC proteins in cancer resistance has been investigated since the characterization of MRP1 (ABCC1)." (PMID 22837662, 2012). "ATP-binding cassette (ABC) transporters confer multidrug resistance in various cancers and ABCC1 overexpression has been shown to contribute to drug resistance in the CHL cell line, KMH2." (PMID 22871336, 2012). "ABCB5 is a member of the ABC protein superfamily, which includes the transporters ABCB1, ABCC1 and ABCG2 responsible for causing drug resistance in cancer patients and also several other transporters that have been linked to human disease." (PMID 21298007, 2011). "So far, tissue culture studies have consistently shown that the major mechanism of MDR in most cultured cancer cells involves ABCB1(also known as P-glycoprotein, P-gp, or MDR1), ABCC1 (also known as multidrug resistance associated-protein 1, MRP1), or ABCG2." (PMID 20628484, 2010). "Chemotherapy resistance has been a huge obstacle in cancer treatment, and multidrug transporters like ABCC1 provide promising targets in chemotherapy and valuable information for drug development." (PMID 20707922, 2010). "On the other hand, clinically attainable but non-toxic doses of vandetanib were found to significantly enhance the sensitivity of MDR cancer cells to ABCC1 or ABCG2 substrate antitumor drugs." (PMID 19390592, 2009). "In addition to ABCB1, efflux transporters ABCG2 and ABCC1 are also well known for their role in cancer chemoresistance." (PMID 40362377, 2025). "In this work, we first disclosed the widely potent reversing effects of KSQ‐4279, a highly‐selective USP1 inhibitor currently in clinical trial (Phase I) for advanced solid tumors (NCT05240898), on ABCB1/ABCG2/ABCC1‐induced MDR cancers, and the exact mechanisms behind were elucidated." (PMID 41328326, 2025). "Finally, FN1 can, for example, activate the integrins α5β1 and α4β1, which increase the ability of cancer cells to transport drugs like doxorubicin out of the cytoplasm via the drug transporter ABCC1." (PMID 40096084, 2025). "Therefore, ABCB1/ABCG2/ABCC1 are recognized as promising targets for the circumvention of MDR in cancer patients." (PMID 41328326, 2025). "Therefore, this study aimed to investigate the influence of SNPs in ABC family transporter genes (ABCB1 rs1128503, ABCC1 rs246240, and ABCC2 rs717620) and the CEP72 gene (rs924607) on the risk of VIPN in a Caucasian pediatric population diagnosed with cancer." (PMID 39201483, 2024). "The P-gp transporter and MDR-associated proteins, MRP1 and ATP binding cassette subfamily C member 1 (ABCC1), are particularly relevant to cancer chemotherapy, as are the breast cancer resistance proteins, BCRP and ABCG2, which are encoded by GTPase-activating protein MDR1 (MDR1) genes." (PMID 37450923, 2024). "Among the many ABC transporters, subfamily members as P-glycoprotein (shorted as P-gp, encoded by ABCB1 gene), BCRP (referred to the breast cancer resistance protein, encoded by ABCG2 gene) and MRP1 (the multidrug resistance associated protein 1, encoded by ABCC1 gene) are the key triggers of MDR." (PMID 38872211, 2024). "TR28, who received two cycles of the combination of gemcitabine and cisplatin as neoadjuvant chemotherapy, has the most prominent initial expression of all three ABCB1 transporters, particularly ABCC1 (in both cancer and stromal cells) that is responsible for cisplatin-induced drug resistance." (PMID 38893104, 2024). "ABCC1, the first transporter to be identified and characterized as a contributor to multidrug chemoresistance in human small‐cell lung carcinoma cell lines, is reported to be closely involved in multidrug resistance development in various cancers." (PMID 38102848, 2023).